NPM1 (nucleophosmin 1)
Diseases named in the same sentence as NPM1 in open-access papers (continued):
Sharing a sentence is not in itself a finding about the gene and the disease.
tumor (continued). "ISRIB supressed proliferation in NPM1-proficient tumors, but significantly increased proliferative capacity in NPM1-deficient tumors, suggesting that both NPM1 and the ISR contribute toward tumor maintenance." (PMID 41413654, 2026). "NPM1 is highly expressed in proliferating cells and various solid tumors and promotes tumor development, consistent with CSN6's oncogenic role." (PMID 41114465, 2026). "In AML, the interactions between GA in NPM1, KMT2A, and menin protein have been linked to leukemogenesis and represent new potential targets for anti-tumor therapies, including menin inhibitors (such as revumenib, ziftomenib, bleximenib, and DSP-5336)." (PMID 40867339, 2025). "NPM1 is involved in several biological processes, such as mRNA splicing, chromatin remodeling, embryogenesis, tumor suppression, and cell apoptosis." (PMID 40136427, 2025). "Further functional assays demonstrated that the reintroduction of NPM1 partly reversed the growth arrest, apoptosis, and ferroptosis of tumor cells induced by AURKB knockdown." (PMID 39927464, 2025). "While this mechanism is consistent with previous studies showing that activated NPM1 supports tumor cell proliferation, migration, and invasion, primarily via the EGFR/MAPK signaling pathway, the precise molecular underpinnings remain to be fully elucidated." (PMID 41145488, 2025). "Among these, full-length nucleophosmin 1 (NPM1) was detected at the cell surface (csNPM1) across multiple tumor models." (PMID 40973767, 2025). "In vivo, EAPB02303 potently reduced the leukemic burden and improved organ tumor infiltration in both wt-NPM1 and NPM1c AML xenograft mice." (PMID 40427634, 2025). "Functional studies demonstrated that SERPINB3 overexpression (but not the RCL-deleted mutant, SERPINB3△6) promotes LUAD cell proliferation and tumor growth, with NPM1 sumoylation being critical for this oncogenic effect." (PMID 41444337, 2025). "NPM1 is highly expressed in various solid tumors and is considered an important target for tumor therapy." (PMID 41234771, 2025). "The highly expressed AURKB in RMS contributes to the apoptosis and ferroptosis resistance of tumor cells through the nucleophosmin 1 (NPM1)/Sp1 transcription factor (SP1)/acyl-CoA synthetase long-chain family member 5 (ACSL5) axis." (PMID 39927464, 2025). "Nucleophosmin 1 (NPM1), a nucleolar phosphoprotein, suppresses tumour immunogenicity by binding to IRF1 and preventing its association with the NLRC5 and CIITA promoters." (PMID 40673641, 2025). "In vivo, experiments further demonstrated that NPM1 had a certain inhibitory effect on tumor growth." (PMID 40393983, 2025). "Then, by querying NPM1 expression within the tumor microenvironment and comparing between adjacent normal, healthy and tumor tissues, we found that it is particularly expressed in tumor epithelial cells." (PMID 41145488, 2025). "Once in the extracellular space, HMGA1 initiates autocrine or paracrine signaling leading to the hyperphosphorylation of NPM1, thereby promoting tumor proliferation." (PMID 41145488, 2025). "NPM1 affects the stability and localization of many base excision repair proteins, such as the alternative reading frame tumor suppressor p14ARF and the apurinic/apyrimidinic endonuclease 1 (APE1)." (PMID 39120297, 2024). "Compared to WT mice, Npm1+/− mice developed more tumors and a greater number of larger tumors, indicative of a higher tumor burden." (PMID 39103576, 2024).
tumor (continued). "In the nuclei of normal cells, NPM1 proteins form large homologous complexes that bind to and stabilize Fbw7γ, a tumor suppressor and E3-ubiquitin ligase." (PMID 37762644, 2023). "The human nucleophosmin 1 (NPM1) gene is multifunctional, including chromatin remodeling, ribosome biogenesis, genomic stability, regulation of tumor suppressors, and transcription factors." (PMID 36808479, 2023). "NPM1 is an abundant nucleolar chaperone that, in addition to facilitating ribosome biogenesis, contributes to nucleolar stress responses and tumor suppression through its regulation of the p14 Alternative Reading Frame tumor suppressor protein (p14ARF)." (PMID 38106181, 2023). "NPM1 acts as an oncogene and a tumour suppressor in tumourigenesis, depending on the cell type and the expression levels of proteins." (PMID 37251542, 2023). "The multitude of cellular activities NPM1 can interact with explains how NPM1 can exhibit both oncogenic and tumor-suppressor functions in the cell." (PMID 35054502, 2022). "Recently, we also reported that Puf-A is a novel assembly factor involved in ribosome biogenesis and is required for cancer growth and tumor progression through its interactions with NPM1." (PMID 35563782, 2022). "NPM1 is involved in tumor progression, especially with the role in ribosome biogenesis that is increased in cancer cells." (PMID 34999733, 2022). "In agreement with CIGB-325 interactome from tumor cells, nucleolar protein B23/NPM1 was also identified in our study." (PMID 35336959, 2022). "NPM1 has a greatly heterogeneous role in the cell and interacts with both oncogenic and tumor-suppressing cellular functions." (PMID 35054502, 2022). "The four remaining categories include aberrations in the Nucleophosmin (NPM1) gene, tumor suppressors and members of the spliceosome- and cohesin complexes." (PMID 35986270, 2022). "In conclusion, this is the first comprehensive study to examine NPM1 expression in relation to m6A, cuproptosis and tumor cell immune infiltration in gastrointestinal cancer." (PMID 36188614, 2022). "Emerging evidence indicates an essential role of the NPM1 overexpression in distinct human neoplasms." (PMID 36282861, 2022). "Studies have shown that the content of NPM1 in tumor cells and growing cells is significantly higher than that in quiescent cells." (PMID 34335635, 2021). "In this setting, CYCLON and NPM1 IHC staining interpretation would simply rely on the identification of their subcellular localization in DLBCL tumor cells, which can be easily distinguished by expert pathologists." (PMID 34885010, 2021). "With the NPM1 wild-type form, this equilibrium favors the nuclear localization at steady state, which is observed in most normal and tumor tissues." (PMID 34885010, 2021). "The NPM1 IHC score in tumor sample tissue was significantly higher than that in paracancerous tissue." (PMID 34335635, 2021). "NPM1 overexpression can increase ribosome biogenesis and protein synthesis and can accelerate DNA repair of tumor cells." (PMID 33628783, 2021). "Krumbholz and colleagues created a nested multiplex PCR assay to detect the genomic NPM1-ALK genomic breakpoints in tumor material." (PMID 33921029, 2021). "The NPM1–ALK fusion protein is expressed in the nucleus and the cytoplasm of the tumor cells, whereas all variant ALK fusion proteins are located in the cytoplasm only." (PMID 33921029, 2021). "Five tumor suppressor genes have variants (RNF43 G659fs, NPM1 W288fs, RPL22 K15fs, ACVR2A K437fs, LARP4B T163fs) that occur in over 5% of samples in at least one cohort." (PMID 34214079, 2021). "Overall, the NPM1 effect in tumorigenesis appears to be complex and probably context-specific, varying amongst different tumor types." (PMID 34885010, 2021).
tumor (continued). "IHC staining of the tumor tissues demonstrated that the expression of PD-L1 was decreased when NPM1 was knocked down, supporting that NPM1 modulated T cell activity by regulating PD-L1 expression in mouse model." (PMID 32245950, 2020). "It has been highlighted that, in some cases, NPM1 increased expression correlates with the mitotic index and with the stage of tumor progression." (PMID 32664415, 2020). "This idea was recently investigated using the NPM1 interaction with the tumor suppressor Fbw7γ as a model system." (PMID 32664415, 2020). "Such modification facilitates RPS10's ability to interact with NPM1 (nucleophosmin 1, a factor functioning in ribosome assembly), which ensures proper ribosome assembly, and general protein synthesis, supporting tumor cell proliferation." (PMID 32743345, 2020). "Our results showed that NPM1 knockdown significantly decreased the tumor size, and reduced the occurrence rate of pulmonary metastasis as well as the number of nodules formed in lungs." (PMID 32245950, 2020). "All these data demonstrate that, not only the presence of APE1 and NPM1, but also their functional interaction, plays a major role in protecting tumor cells from CDDP-induced cytotoxicity." (PMID 31307523, 2019). "STAT5A is a tumour suppressor protein which is capable of reciprocally suppressing NPM1-ALK gene expression by selectively binding to the enhancer region." (PMID 31366041, 2019). "Critically, despite wild-type ALK expression being typically restricted to neural tissues, expression of the NPM1-ALK fusion protein ectopically occurs in NPM1-ALK+ tumour cells via the NPM1 promoter as a result of the t2;5(p23;q25) translocation." (PMID 31366041, 2019). "Barplot summarizing the statistically significant correlations (p ≤ 0.05) existing between APE1 and NPM1 expression levels in twenty-five TCGA tumor samples." (PMID 31307523, 2019). "Major reduction in tumor mass (7 mm residual tumor) and NPM1 negativity were achieved after one block of FLAG (fludarabine, cytarabine, filgrastim) and two blocks of FLAG-mitoxantrone." (PMID 30859798, 2019). "SHP1 is a tumour suppressor, which functions as a negative regulator of NPM1-ALK and several signal transduction proteins (such as cytokine receptors) by dephosphorylating the receptor itself and/or receptor-associated kinases." (PMID 31366041, 2019). "Knockdown of NPM1 abrogated the tumor-promoting function of DDX27, as indicated by MTT assays, without affecting DDX27 expression." (PMID 29535419, 2018). "It is reported that NPM1 is associated with nuclear NF-κB p65 to enhance the DNA binding activity of NF-κB in response to TNF-α stimulation, and that NPM1 and NF-κB are likely to act cooperatively to regulate tumor progression." (PMID 29535419, 2018). "Eventually, NPM1 suppression decreased wound healing and tumor invasion capability of A549-CUG2 and BEAS-CUG2 cells." (PMID 27974707, 2017). "In consideration of its multifunctional potentiality NPM1 can play roles both as a proto-oncogene and as a tumor suppressor." (PMID 28686225, 2017). "NPM1 is a multifunctional protein overexpressed in proliferating cells such as tumor cells and has been proposed as a marker of different solid tumors." (PMID 26993766, 2016). "CIGB300 has demonstrated pharmacological activity against a large panel of tumour cell lines where NPM1 is overexpressed and in mice xenografts." (PMID 27058426, 2016). "NPM1 is involved in maintaining genome stability and regulating apoptosis, and, as such, has been described as having both oncogenic and tumor suppressive functions." (PMID 27553022, 2016). "NPM1 and its two phosphorylated forms were found at increased levels in tumor cells as compared with that in peri-tumoral normal cells." (PMID 26993766, 2016). "Consistent with a multifunctional role within the cell, NPM1 can function not only as a proto-oncogene but also as a tumor suppressor." (PMID 27553022, 2016).
tumor (continued). "First, NPM1 overexpression is correlated to increased ribosome biogenesis and protein synthesis and both these functions are amplified in tumour cells." (PMID 27058426, 2016). "We previously demonstrated that the multivalent pseudopeptide N6L binds to NPM1 potently affecting in vitro and in vivo tumor cell growth of various tumor types as well as angiogenesis." (PMID 26993766, 2016). "All of these biological effects have been demonstrated to be correlated with NPM1 overexpression in tumor cells." (PMID 25779011, 2015). "Studies of the mechanisms by which NPM1 promotes tumor growth mainly focus on ribosome biogenesis or its anti-apoptotic effects in the cytoplasm." (PMID 26068981, 2015). "The role of NPM1 in cancer development remains complex and NPM1 has been ascribed both pro-tumorigenic and tumor suppressive functions." (PMID 26559910, 2015). "Due to the diversity of cellular activities exhibited, NPM1 is a key player with dual functions of either a potential oncogene or a potential tumor suppressor." (PMID 25779011, 2015). "Quantitative analysis confirmed that high staining scores of NPM1 also exist in peri-tumor tissues, but the proportion of high staining scores is significantly less than in tumor tissues." (PMID 26068981, 2015). "Taken together, much evidence suggests that NPM1 is highly expressed in various tumors and is correlated with the stage of tumor progression and poor prognosis." (PMID 25779011, 2015). "Particularly, NPM1 expression presented correlation with tumor malignant progression as lower expressions were observed in non-neoplastic tissue, AST II and OLI II compared to the expressions of GBM and OLI III." (PMID 26108672, 2015). "There were also two processes associated to bone “myelopoiesis of bone marrow” (associated genes NPM1, RARA) and “quantity of trabecular bone” (associated genes CREBBP, SMO)—these findings were present only in the tumour tissue." (PMID 25496518, 2014). "The correlation between NPM1 and the stage of tumor progression aslo have been observed in some patients." (PMID 25663821, 2014). "NPM1, which played an important role in chemoresistance of tumor cells, was also up-regulated in brain tissues of GBM compared to normal tissues." (PMID 24747515, 2014). "And expression of NPM1 is higher in many types of tumor and proliferating cells than in normal resting cells." (PMID 25663821, 2014). "Previously, our group described biochemical and structural variability of NPM1 in tumor and differentiating cells, indicated by differences in epitope exposure, granzyme B recognition and resistance to SDS denaturation." (PMID 25490769, 2014). "Nucleophosmin (NPM1)/B23 is an abundant, nucleolar autoantigen and tumor antigen that is over-expressed in rapidly proliferating cells." (PMID 25490769, 2014). "In both subcellular compartments, the NPM1 immunoreactivity presented a large inter- and intra-tumor heterogeneity." (PMID 24410879, 2014). "In the present study, NPM1 protein expression was significantly down-regulated in GC, which supports its role as a tumor suppressor." (PMID 24410879, 2014). "Nevertheless several studies revealed that, paradoxically, NPM1 is able to both act as a tumour suppressor and as a proto-oncogene during tumourigenesis." (PMID 24796332, 2014). "The score of NPM1 immunoreactivity in the nucleoli of tumor cells was inversely correlated with the protein expression by Western blot (r = -0.693, p = 0.039; by Spearman’s correlation)." (PMID 24410879, 2014). "We also show that high levels of NPM1 positively impact cell proliferation and cell migration, thus participating in the control of tumour growth." (PMID 24796332, 2014). "On the other hand, NPM1 is a potential tumor suppressor by maintaining chromosome stability and regulating ARF activity." (PMID 22631075, 2012).
tumor (continued). "NPM1 is an abundant protein in tumor cell lines and hence NPM1 is more likely to regulate RPS9 localization than the other way around." (PMID 23285058, 2012). "At the moment, NPM1 is believed to employ sophisticated mechanisms to engage in oncogenic and tumor suppressor pathways." (PMID 23271972, 2012). "Accumulative evidence suggested that highly expressed NPM1 correlated with the stage of tumor progression and poor prognosis." (PMID 22631075, 2012). "In these malignancies, NPM1 contributes to tumor development by activating the oncogenic potential of the fused protein partner, that is, ALK, RARα, or MLF1." (PMID 21152184, 2011). "Rather, NPM1 acts as a context dependent tumor suppressor, that is downstream of the cell cycle machinery and expression level and localization of the protein is of major importance." (PMID 21152184, 2011). "Mechanisms of NPM1 nuclear export functions of NPM1 in the nucleolus and at the mitotic spindle are discussed in relation to tumor development." (PMID 21152184, 2011). "The gene NPM1, which codes for nucleophosmin, is frequently overexpressed and rearranged in human cancer and has proto-oncogenic and tumor suppressor features." (PMID 19250532, 2009). "Indeed, in our animal model study, both CSN6 KD (leading to NPM1 decrease) and the NPM1 inhibitor NSC348884 showed strong efficacy in tumor inhibition and gemcitabine sensitization." (PMID 41114465, 2026). "Notably, the surrounding normal epithelium maintained Npm1 deletion, suggesting a tumor-specific requirement for NPM1 during initiation." (PMID 41413654, 2026). "In PDAC, NPM1 has a role in tumor progression and chemotherapy resistance." (PMID 41145488, 2025). "Interestingly, NPM1 can act as either an oncogene or a tumor suppressor, depending on the cell type." (PMID 40438109, 2025). "The reintroduction of SP1 could partially reverse the apoptosis and ferroptosis of tumor cells induced by NPM1 knockdown." (PMID 39927464, 2025). "Here, we provide evidence that NPM1 is expressed on the cell-surface in a tumor-selective manner." (PMID 40269321, 2025). "In numerous tumor types, alterations in NPM1 have been observed." (PMID 41234771, 2025). "Notably, similar to other mutations affecting DNA methylation regulators such as NPM1, IDH2, and CEBPA, DNMT3A mutations have also been shown to upregulate tumor-specific antigens, which in turn can activate antigen-specific clonal T cell responses." (PMID 40861464, 2025). "Further functional assays demonstrated that knockdown of AURKA significantly impaired the proliferation and induced ferroptosis of ES cells, while overexpression of NPM1 partly reversed the proliferation arrest and ferroptosis of tumor cells induced by AURKA knockdown." (PMID 38287009, 2024). "In addition, NPM1 has shown increased interest in radiotherapy, where its knockdown significantly reduces tumor cell survival after irradiation." (PMID 39120297, 2024). "Similarly, genes such as NME2 and NPM1, which play a role in cell cycle and tumor suppression, were consistently downregulated in both datasets." (PMID 40692702, 2024). "Based on these observations, Teppert and coworkers have developed a double-targeting immunotherapy combining CAR and TCR technologies: CAR’TCR-T cells, co-expressing CD33-CAR and a transgenic dNPM1-TCR, showed potent and prolonged anti-tumor activity against NPM1-mutant AMLs." (PMID 39518068, 2024). "First, we functionally validated the role of NPM1 as a tumour promoter." (PMID 37251542, 2023).